ZNF335 (zinc finger protein 335)
Description:
Component or associated component of some histone methyltransferase complexes may regulate transcription through recruitment of those complexes on gene promoters. Enhances ligand-dependent transcriptional activation by nuclear hormone receptors. Plays an important role in neural progenitor cell proliferation and self-renewal through the regulation of specific genes involved brain development, including REST. Also controls the expression of genes involved in somatic development and regulates, for instance, lymphoblast proliferation.
Synonyms: NIF-1; bA465L10.2; MCPH10; NIF1; NIF2
Tractability: PROTAC: UniProt records ubiquitination sites on it; ubiquitination databases record sites on it.
Gene: Protein-coding gene on chromosome 20 (45,948,653 to 45,972,206, reverse strand). Ensembl gene ENSG00000198026.
Subcellular location: Nucleus
Subcellular location (Human Protein Atlas): Nucleoplasm
Pathways (Reactome):
Developmental Biology: Activation of anterior HOX genes in hindbrain development during early embryogenesis
Gene Ontology:
Molecular function: protein binding; DNA-binding transcription factor activity; transcription cis-regulatory region binding; histone methyltransferase binding; RNA polymerase II cis-regulatory region sequence-specific DNA binding
Biological process: brain development; epigenetic regulation of gene expression; positive regulation of lymphocyte proliferation; positive regulation of neurogenesis; neuron projection morphogenesis; positive regulation of neuroblast proliferation; regulation of DNA-templated transcription; positive regulation of cell population proliferation
Cellular component: histone methyltransferase complex; nucleoplasm; nucleus
Genetic constraint (gnomAD): Loss-of-function variants: 84 observed, 140.18 expected, observed/expected ratio (o/e) 0.6, 90% interval 0.5 to 0.72. The upper end of that interval is the gene's LOEUF score, 0.72, which puts it in group 2 of 6, group 1 being the genes least tolerant of losing a copy. Missense variants: 1,837 observed, 1,774.5 expected, observed/expected ratio (o/e) 1.04, 90% interval 1 to 1.08. Synonymous variants: 751 observed, 708.04 expected, observed/expected ratio (o/e) 1.06, 90% interval 1 to 1.13.
Homologues: Orthologues: chimpanzee ZNF335 (99% identical), macaque ZNF335 (98% identical), pig ZNF335 (92% identical), rabbit ZNF335 (92% identical), guinea pig ZNF335 (91% identical), rat Zfp335 (87% identical), mouse Zfp335 (87% identical), dog ZNF335 (87% identical), zebrafish znf335 (53% identical), tropical clawed frog ZNF335 (43% identical), Drosophila melanogaster CG9932 (15% identical), Drosophila melanogaster CG8388 (9% identical), and 7 more. Paralogues in human: ZFP64 (11% identical).
Diseases named in the same sentence as ZNF335 in open-access papers:
ZNF335 is named in the same sentence as 18 diseases in open-access papers, as found by Europe PMC text mining. Sharing a sentence is not in itself a finding about the gene and the disease. The quoted sentences say what the papers report.
microcephaly (6 papers, 2014 to 2022). A congenital or acquired developmental disorder in which the circumference of the head is smaller than normal for the person's age and sex. "Humans carrying homozygous or compound heterozygous mutations in either ZNF335 or ANKLE2 exhibit severe microcephaly like that characteristic of Zika patients." (PMID 36202870, 2022). "We have also previously used RNA-seq to confirm a splicing defect that we had first identified by traditional molecular biology methods in the ZNF335 gene causing microcephaly." (PMID 28630177, 2017). "Despite these results, a recent study points to a role for REST in human neurogenesis and microcephaly through regulation of REST by a factor, ZNF335, mutated in patients with a severe form of microcephaly." (PMID 26745185, 2016). "ZNF335 is associated with the disease microcephaly (a neurodevelopmental disorder), small somatic size and neonatal death." (PMID 25372662, 2014). "Based on the mechanism revealed in this study, it is possible that microcephaly resulting from Zika infection or loss of ZNF335 or ANKLE2 may be driven by cGAS/STING-dependent apoptosis of neuronal progenitors and/ or CNS immune cells." (PMID 36202870, 2022). "Many genes have been implicated in the development of microcephaly (summarized inTable 1) includingASPM,MCPH1,CDK5RAP2,CEP152,CENPJ,WDR62,STIL,CASC5,CEP135,ZNF335,PHC1,CDK6, with many of them contributing to centrosome and spindle protein dysfunction during mitosis." (PMID 26535115, 2015).
autosomal recessive primary microcephaly (3 papers, 2021 to 2023). Autosomal recessive primary microcephaly (MCPH) is a rare genetically heterogeneous disorder of neurogenic brain development characterized by reduced head circumference at birth with no gross anomalies of brain architecture and variable degrees of intellectual impairment. "Another study reported variants of ZNF335 (MCPH10, #615095) that cause “severe autosomal recessive primary microcephaly” even though the patients exhibit cardiac, eye, limb, and digital defects, thus consistent with the definition of syndromic MCPH." (PMID 36831309, 2023). "ZNF335 and ANKLE2 are responsible for regulating the proliferation and differentiation of neuronal progenitor cells, and both are candidate genes of autosomal recessive primary microcephaly, which is characterized by reduced skull circumference and brain volume." (PMID 35456484, 2022).
autoimmune disease (1 paper, 2023). A disorder resulting from loss of function or tissue destruction of an organ or multiple organs, arising from humoral or cellular immune responses of the individual to their own tissue constituents. "We thus examined the relationship between ZNF335 expression and the eTreg population in patients with autoimmune diseases." (PMID 37843279, 2023). "Thus, the positive correlation between ZNF335 expression and human eTregs suggests a potential role of ZNF335 in human eTreg differentiation, and the reduction in ZNF335, HADHA, and MitoTracker expression in human Tregs may be associated with the pathogenesis of autoimmune diseases." (PMID 37843279, 2023).
somatotropinomas (1 paper, 2025). "Among the genes included in this pathway, recent studies have suggested that FANCD2, SPTA1, TYRO3, and ZNF335 genes are emerging as key players in immune response and regulating tumorigenesis, even if their role has not been studied in TME of somatotropinomas." (PMID 40415137, 2025).
ZNF335 also shares sentences with these, for which no sentence is quoted: celiac disease (2 papers); bladder cancer (1); cancer (1); cone-rod dystrophy (1); deafness (1); Epileptic encephalopathy (1); limb girdle muscular dystrophy type 2S (1); mitochondrial DNA depletion syndrome (1); neurodevelopmental disorder (1); pneumonia (1); Primary microcephaly (1); Progressive microcephaly (1); Spastic tetraplegia (1); Zika (1).